BRD7 (bromodomain containing 7)
Diseases named in the same sentence as BRD7 in open-access papers (continued):
Sharing a sentence is not in itself a finding about the gene and the disease.
breast carcinoma (continued). "BRD7 may also interfere with breast cancer progression through inactivation of the HIF1α/LDHA transcriptional axis and via promotion of BRCA1-mediated transcriptional regulation of the estrogen receptor expression 10,15." (PMID 33531996, 2021). "In addition, in vitro tests indicated that BRD7 has the ability to inhibit mobility, migration and invasion of breast cancer cells." (PMID 34948142, 2021). "Moreover, an unfavorable overall survival was observed in breast cancer patients with a combination of low BRD7 expression and high YB1 expression." (PMID 32028981, 2020). "The developmental mechanism of BRD7-mediated malignant features could be helpful for designing personalized treatments for breast cancer." (PMID 32028981, 2020). "Therefore, our aim was to gain insight into the function and molecular biological mechanism of BRD7 involved in breast cancer growth, invasion and metastasis." (PMID 32028981, 2020). "However, the roles of BRD7, its association with YB1, and the molecular mechanism by which it is involved in tumor invasion and metastasis in breast cancer are not well understood and remain to be determined." (PMID 32028981, 2020). "Additionally, BRD7 expression was negatively correlated with the level of YB1 in breast cancer patients." (PMID 32028981, 2020). "Collectively, these results suggest that BRD7 might regulate the proliferation and migration of breast cancer cells by regulating YB1 at the posttranslational level." (PMID 32028981, 2020). "Importantly, the results of CCK8 assays showed that BRD7 overexpression significantly inhibited the growth of breast cancer cells compared with control cells." (PMID 32028981, 2020). "As an important tumor suppressor gene, BRD7 plays an anti-tumor role in breast cancer." (PMID 32028981, 2020). "Therefore, we speculated that TRIM25 participated in the malignant progression of breast cancer by regulating the BRD7/YB1 axis." (PMID 41315221, 2025). "Consequently, these findings reveal that TRIM25 promotes ubiquitination-mediated degradation of BRD7 and promotes breast cancer progression and paclitaxel resistance via the YB1-Bcl-2 axis, which provides a new prognostic predictor and therapeutic target for breast cancer." (PMID 41315221, 2025). "Thus, we have shown that TRIM25 negatively regulates the stability of BRD7 protein through the ubiquitin-proteasome pathway, and confirmed the direct binding domains of TRIM25 and BRD7, which provide the molecular basis for further development of targeted therapy for the treatment of breast cancer." (PMID 41315221, 2025). "However, the mechanism how BRD7 functions as tumor suppressor roles in breast cancer remains unclear." (PMID 35371302, 2022).
breast carcinoma (continued). "In addition, BRD7 increased the expression of epithelial molecules such as E-cadherin and Claudin1 and decreased the expression of mesenchymal molecules such as Snail and vimentin in breast cancer cells." (PMID 32028981, 2020). "However, the function and underlying molecular events of BRD7 in tumor invasion and metastasis in breast cancer are not fully understood." (PMID 32028981, 2020). "BRD7 is usually under expressed and plays a role as a tumor suppressor in many malignant tumors; in addition, it is associated with advanced disease and poor prognosis in cancers such as nasopharyngeal cancer (NPC), breast cancer, ovarian cancer, lung cancer and liver cancer." (PMID 32028981, 2020). "Our results confirmed that TRIM25 was involved in the malignant progression of breast cancer and PTX resistance, and that TRIM25 participates in the regulation of ubiquitination level and protein degradation of BRD7 through the ubiquitin-proteasome pathway." (PMID 41315221, 2025). "Additionally, TRIM25 decreased the protein stability of BRD7 through the ubiquitin proteasome pathway by increasing the K48-linked ubiquitination of BRD7 at the K119 site, and then activated the YB1/Bcl-2 signal axis, thus mediating malignant progression and PTX resistance of breast cancer." (PMID 41315221, 2025). "In order to further confirm the important role of the TRIM25/BRD7 axis in paclitaxel resistance of breast cancer, we detected the differential expression of TRIM25 and BRD7 between PTX-resistant BC cells and their parent cells." (PMID 41315221, 2025). "To better understand the potential clinical correlation between TRIM25 and BRD7, we detected the expression of TRIM25 and BRD7 in 34 normal breast tissues and 219 breast cancer biopsies." (PMID 41315221, 2025). "Collectively, our data revealed that BRD7 is essential for TRIM25-induced malignant progression and PTX chemoresistance of breast cancer cells." (PMID 41315221, 2025). "Taken together, these data validate that TRIM25 promotes breast cancer tumorigenesis and PTX chemotherapy resistance by negatively regulating the stability of BRD7 protein in vivo." (PMID 41315221, 2025). "To further reveal the mechanism of BRD7’s involvement in development and PTX chemotherapy sensitization in breast cancer, we screened and identified a potential E3 ubiquitin ligase, TRIM25, interacting with BRD7 by IP-MS in our previous study." (PMID 41315221, 2025). "Previous studies have demonstrated that the tumor suppressor gene BRD7 interacts with YBX1 to facilitate its degradation and consequently inhibit epithelial–mesenchymal transition and metastasis in breast cancer." (PMID 38520004, 2024). "To identify the molecular events induced by BRD7 and YB1 in breast cancer cell invasion, we revisited our RNA-seq data (PRJNA562788) and the public database (GSE60964 and GSE6562) by GSEA." (PMID 32028981, 2020). "In previous studies, we have confirmed that BRD7 is a highly unstable protein in breast cancer, and TRIM28‐mediated BRD7 instability is a significant mechanism contributing to the onset and development of breast cancer." (PMID 41510594, 2026). "Additionally, we found that BRD7 was lowly expressed at the transcriptional levels in NPC and breast cancer, and it was negatively regulated by c‐Myc, resulting in its downregulation at the transcriptional level." (PMID 41510594, 2026). "In addition, our previous study proved that BRD7 reduced the stability of YB1 protein through the ubiquitin-proteasome pathway and inhibited the malignant progression of breast cancer." (PMID 41315221, 2025).
breast carcinoma (continued). "Therefore, we suspect that BRD7 mediates the process of TRIM25 promoting the occurrence and development of breast cancer and PTX resistance." (PMID 41315221, 2025). "Previous studies have shown the key role of BRD7 in suppressing cell proliferation, blocking cell cycle processes, inducing cell apoptosis, suppressing cell migration and invasion, and promoting sensitivity to PTX chemotherapy in breast cancer." (PMID 41315221, 2025). "Altogether, this study verified the mechanism by which the TRIM25/BRD7/YB1/Bcl-2 axis is involved in the malignant progression and PTX resistance of breast cancer, providing a novel insight into BC development and potential targets for improving the PTX therapeutic resistance." (PMID 41315221, 2025). "In our previous study, BRD7 interacted with YB1 and negatively regulated the phosphorylation of YB1 at Ser102, promoting the ubiquitination and degradation of YB1, thus effectively inhibiting the invasion and metastasis of breast cancer cells." (PMID 41315221, 2025). "Bromodomain-containing 7 (BRD7) subunit is present uniquely in the PBAF complex, which usually serves as a tumor-suppressor gene and is downregulated in multiple cancers, such as breast cancer, HCC, ovarian cancer, and colorectal carcinoma." (PMID 34671561, 2021). "As a member of the bromodomain-containing protein family, BRD7 contributes to the inhibition of cell proliferation and cell cycle progression and to the induction of apoptosis in several types of cancers, including NPC and breast cancer." (PMID 32028981, 2020). "Overall, our data suggest that BRD7 might inhibit cell migration, invasion and metastasis through negatively regulating the EMT process in breast cancer." (PMID 32028981, 2020). "Moreover, through its N-terminus, BRD7 binds to Y box binding protein-1 (YB1), an oncogene that is upregulated in certain cancers; this in turn leads to ubiquitin-mediated degradation of YB1 in the MDA231 and MCF7 breast cancer cell lines." (PMID 32992509, 2020). "Nevertheless, the functions and mechanisms of TRIM25 in the malignant progression of breast cancer and PTX resistance, as well as its regulatory relationship with BRD7, are still not clear." (PMID 41315221, 2025). "However, the functions and mechanisms of TRIM25 in the malignant progression and PTX resistance of breast cancer, as well as the regulatory relationship between TRIM25 and BRD7, have not been determined." (PMID 41315221, 2025). "Several BrD members, namely BRPF1, SMARCA4, BRD7, BRD9, BAZ1B, ATAD2 and BRD4 are significantly upregulated in basal breast cancer subtype (when compared to less aggressive luminal A and normal‐like subtype), which strongly mimics the results obtained for the mRNA‐SI." (PMID 35049055, 2022).
colorectal cancer (13 papers, 2016 to 2025). A primary or metastatic malignant neoplasm that affects the colon or rectum. "Furthermore, a high level of BRD7 is positively associated with c-Myc expression, clinical stage, and poor prognosis in colorectal cancer patients, further supporting the role of BRF7 in Myc-dependent tumors." (PMID 36674511, 2023). "Other studies have shown that BRD7 promotes the growth of colorectal cancer cells via c-Myc stabilization." (PMID 34771678, 2021). "The expression of BRD7 is downregulated or lost in breast, ovarian, pancreatic, nasopharyngeal, and colorectal carcinomas, as well as in lung adenocarcinoma and osteosarcoma, an expression pattern that is also described for Hpa2 and is typical for tumor suppressors." (PMID 39695102, 2024). "However, immunohistochemistry of colorectal cancer and normal tissues confirms the downregulation of BRD7 protein in the tumor vasculature." (PMID 28951988, 2017). "Other investigators also found that low/absent BRD7 expression was significantly associated with clinicopathological characteristics and poor clinical outcomes in patients with colorectal cancer." (PMID 26919247, 2016). "In addition, various reports have confirmed that BRD7 expression is down-regulated and significantly correlates with clinical outcomes in a broad range of malignant tumors, such as osteosarcoma, prostate cancer, colorectal cancer and epithelial ovarian carcinoma." (PMID 26919247, 2016). "Over-expressed AQP8 in colorectal cancer (CRC) cells can inhibit the PI3K/Akt signaling transduction, which may have a similar effect in OA, and in concert with BRD7, leads to downregulation of PI3K activity in OA." (PMID 37378023, 2023). "In addition, we found that silencing MUC1-C in (i) NCI-H660 neuroendocrine PC (NEPC) cells, (ii) BT-549 triple-negative breast cancer and (ii) SW620 colorectal cancer (CRC) cells results in downregulation of PBRM1, ARID2, and BRD7." (PMID 34163028, 2021).
hepatocellular carcinoma (9 papers, 2016 to 2023). A malignant tumor that arises from hepatocytes. "Our previous study demonstrated that BRD7 acts as a potential tumor suppressor in hepatocellular carcinoma (HCC)." (PMID 33531996, 2021). "HCV infections repress BRD7 expression in vitro, resulting in the dysregulation of hepatoma cell proliferation." (PMID 30521023, 2018). "A recent study showed that activation of Ras/Raf/MEK/ERK pathway increased BRD7 expression in hepatoma cell during HCV infection." (PMID 27957794, 2017). "Furthermore, BRD7 is downregulated in hepatocellular carcinoma, while higher BRD7 expression levels are associated with improved survival of patients with hepatocellular carcinoma, pointing to a tumor-suppressive role of BRD7 in hepatocellular carcinoma." (PMID 32992509, 2020). "Down-regulation of BRD7 expression has been observed in several malignancies and is correlated with poor prognosis of various cancer types, including breast, colorectal, gastric, and prostate cancer, as well as hepatocellular carcinoma, and osteosarcoma." (PMID 30406031, 2018). "This study aimed to investigate BRD7 expression and its tumor suppressive effect in hepatocellular carcinoma (HCC)." (PMID 26919247, 2016).
prostate carcinoma (8 papers, 2014 to 2026). A carcinoma that arises from epithelial cells of the prostate gland. "Expression of BRD7 is reduced in patients with prostate cancer." (PMID 32992509, 2020). "Subsequent studies in our team and other teams also find that BRD7 functions as a tumor suppressor in non-small cell lung cancer (NSCLC), osteosarcoma, endometrial carcinoma, and prostate cancer 27-30." (PMID 35371302, 2022). "The interaction between BRD7 and TRIM24 in prostate cancer cells negatively regulates TRIM24 activity, and diminishes cell proliferation and cell growth." (PMID 32992509, 2020). "Additionally, the identification of bromodomain-containing 7 (BRD7), a negative regulator of cell proliferation and growth, represses the AR transactivation activity induced by TRIM24 and contributing to the modulation of prostate cancer pathogenesis." (PMID 39160596, 2024).
melanoma (7 papers, 2020 to 2023). A malignant, usually aggressive tumor composed of atypical, neoplastic melanocytes. "PBRM1 and BRD7, which are mutated at lower frequency in melanoma than ARID2, were also identified in an unbiased CRISPR/CAS9 screen as modulators of resistance to T cell-mediated killing and sensitivity to immunotherapy." (PMID 35323214, 2022). "BRD7 is mutated or downregulated in various cancers including bladder, endometrial, hepatobiliary, melanoma, and others." (PMID 36605718, 2022). "We found that the TP-472 target BRD7 is overexpressed in melanoma patient samples and associated with a poor prognosis." (PMID 34771678, 2021). "Loss of ARID2 or BRD7 enhanced cytokine secretion in response to IFNγ and sensitized melanoma cells to T cell-mediated cytotoxicity in vitro." (PMID 33409155, 2020). "A CRISPR-Cas9 screen analysis found that ARID2, BRD7, and PBRM1, components of the PBAF complex, sensitized mouse melanoma cells to T-cell cytotoxicity, and PBRM1-deficient murine melanomas were found to be infiltrated by more cytotoxic T cells." (PMID 36361605, 2022). "Collectively, our results identify BRD7/9 inhibitor TP-472 as a potentially useful therapeutic agent for melanoma therapy." (PMID 34771678, 2021). "Based on our results, we suggest that BRD7 is an important new epigenetic regulator of melanoma growth and TP-472 can be employed as a new candidate drug for the effective treatment of melanoma." (PMID 34771678, 2021). "We observed that BRD7/9 are overexpressed in melanoma patient samples at both the mRNA and protein levels, and their overexpression is associated with a poor prognosis." (PMID 34771678, 2021). "Examinations of Human Protein Atlas datasets revealed that overexpression of BET family BRD proteins (i.e., BRD2 and BRD3), BRD9, BRD7, and EZH2 were associated with relatively poor three-year survival in melanoma patients." (PMID 34771678, 2021). "The results of immunohistochemistry analyses of melanoma tissues from the Human Protein Atlas indicated that BRD7, BRD9, BRD4, BRD3, and KDM6B were mostly expressed at >75% level." (PMID 34771678, 2021). "However, a recent study which analyzed publicly available datasets found that BRD7 is over-expressed in melanoma and that expression increases in metastatic disease." (PMID 35323214, 2022). "Our analysis of publicly available melanoma datasets (Riker and Xu melanoma datasets) revealed that BRD7 is significantly overexpressed in metastatic melanoma patient samples as compared to the primary site samples and is also present at higher levels in advanced-stage melanoma patient samples." (PMID 34771678, 2021). "We observed that the expression of several ECM genes was significantly higher in patient-derived melanoma samples compared to the normal skin samples and a few of them are also significantly co-expressed with TP-472 target epigenetic regulator BRD7." (PMID 34771678, 2021). "Therefore, to mimic the clinical scenario, we conducted a long-term clonogenic survival assay using GSK343 (targeting EZH2), JQ1 (targeting BET family BRD proteins-BRD2 and BRD3), TP-472 (targeting BRD7/9) using multiple BRAF mutant melanoma cell lines (M14, SKMEL-28, A375, and A2058)." (PMID 34771678, 2021). "To do so, we first assessed whether TP-472 target BRD7/9 are overexpressed in metastatic melanoma patient samples in the Riker melanoma dataset and associated with advanced disease stage (stage III) in the Xu melanoma dataset." (PMID 34771678, 2021). "To assess the clinical relevance of ECM genes that were downregulated upon TP-472 treatment, we examined whether these ECM genes are overexpressed in melanoma patient samples in a manner similar to the epigenetic regulator BRD7/9 using the Talantov melanoma dataset." (PMID 34771678, 2021).
melanoma (continued). "TP-472, a compound with selective function and similarity to the bromodomain of BRD7 and BRD9, has antitumor activity on melanoma." (PMID 36844227, 2023). "TP-472, a drug that is selective for the highly similar bromodomains of BRD7 and BRD9, markedly inhibited melanoma growth and invasion." (PMID 35323214, 2022). "Our analysis of publicly available Talantov melanoma datasets revealed that only EZH2, BRD7/9, BRD2/3/4, BRPF1, EHMT2, and KDM6B were significantly overexpressed at the mRNA level in patient melanoma tissue samples as compared to the normal skin samples." (PMID 34771678, 2021). "Inactivation of three genes, including polybromo 1 (PBRM1), AT-rich interaction domain 2 (ARID2), and bromodomain containing 7 (BRD7), that code for PBAF, one of the chromatin-remodeling complexes of the SWI/SNF, sensitized melanoma cells for destruction by T cells." (PMID 34827646, 2021).